ALK (ALK receptor tyrosine kinase)
Diseases named in the same sentence as ALK in open-access papers (continued):
Sharing a sentence is not in itself a finding about the gene and the disease.
tumor (continued). "This review aims to provide an overview of underlying molecular alterations of ALK-i resistance and point out promising role of liquid biopsy in predicting tumor response and monitoring resistance mutations." (PMID 36230686, 2022). "ALK gene variants (such as gene rearrangements and mutations) also play a key role in the tumor immune microenvironment." (PMID 35958559, 2022). "We found that this step increased the association between ALK cfDNA and ALK tumor tissue 5-mC signals and therefore reduced the number of genomic regions without tumor-informative DNA methylation." (PMID 36461127, 2022). "The ALK receptor is also expressed at a significantly high level in GBM, and chromosomal rearrangements, amplifications, and mutations of the ALK gene are commonly found and associated with poor survival and a higher tumor grade of GBM." (PMID 35625997, 2022). "DNA from the post‐chemotherapy, resected tumor sample for Case 2 also confirmed loss of the R1275Q ALK mutation by tNGS (G > A in 2/759 reads) with consistent SCAs." (PMID 36029175, 2022). "SNP array results confirmed the tumor cell content amongst samples was adequate to detect the presence of an ALK mutation, especially using the highly sensitive T‐NGS and MassARRAY techniques." (PMID 36029175, 2022). "To identify tumor-associated 5-mC biomarkers in cfDNA, we first generated genome-wide DNA methylation profiles from 66 ALK-positive and 13 healthy control plasma samples by cfMeDIP-seq." (PMID 36461127, 2022). "It effectively overcame secondary ALK mutations, including L1196M and G1202R, in vitro and suppressed tumor growth in xenograft mouse models in vivo." (PMID 34845836, 2022). "Tumor DNA from the patient was further analyzed showing that all three sampled tumor sites—sample 1, sample 2 and sample 3—contained the ALK F1174I mutation." (PMID 36140661, 2022). "Molecular abnormality of the ALK gene is associated with permanent cell proliferation, leading to the growth of multiple tumours, such as non‐small‐cell lung cancer (NSCLC)." (PMID 35855570, 2022). "The median TMB of ALK-positive tumor samples is only 2.29 mutations/Mb (ranging from 0.76 to 16.79 mutations/Mb)." (PMID 35958559, 2022). "Some CT imaging features, such as central tumour location, pleural effusion, lobulated margin, large mass and distant metastases, have been linked to ALK gene rearrangements in these studies." (PMID 36338735, 2022). "Using human tumor biospecimens, we further demonstrate that phosphorylated ALK (p-ALK) expression is associated with resistance to PARP inhibitors and positively correlated with p-Tyr19-CDK9 expression." (PMID 36253486, 2022). "Genetic testing revealed a germline ALK F1174I mutation that was present in all tumor samples as well as in normal tissue samples from the patient." (PMID 36140661, 2022). "This has been reported in NSCLC patients with EGFR mutations and ALK rearrangements, which are also associated with low tumor neoantigen load." (PMID 34208113, 2021). "Approximately half of the IMT have a translocation that activates ALK gene located at 2p23; this mutation is more frequently reported in tumours of gynaecological origin, even as high as 80–100% depending on the series." (PMID 34801049, 2021). "This is further reinforced by a recent report in which 41% of NB tumour samples expressed high levels of ALK protein, which is in excess of the estimated 8–10% of primary NB that harbours an ALK mutation." (PMID 33411331, 2021). "NB tumor tissues express full‐length ALK and exhibit single‐base missense mutations in the kinase domain of ALK, which promote ligand‐independent signaling." (PMID 33155698, 2021).
tumor (continued). "In particular, a second molecular analysis after resistance to first- and second-generation ALK-TKIs revealed a high PD-L1 expression and tumor mutation burden." (PMID 34804000, 2021). "Our data suggest that the specific binding of CCC-003 to mutated DNA within the ALK gene exerts its anti-tumor activity through a mode of action that is distinct from those of other ALK inhibitors." (PMID 34591871, 2021). "Although multiple ALK-TKIs benefit extending survival, it is inevitable to appear tumor relapse caused by acquired resistance." (PMID 33627640, 2021). "The NPM1–ALK fusion protein is expressed in the nucleus and the cytoplasm of the tumor cells, whereas all variant ALK fusion proteins are located in the cytoplasm only." (PMID 33921029, 2021). "The tyrosine kinase receptor anaplastic lymphoma kinase (ALK) has been linked to the development of many tumours." (PMID 35356629, 2021). "Four tumor samples with confirmed fusions from clinical variant analysis, three in ALK and one in ROS1, were further analyzed with AVENIO FFPE, where neither of the fusions were detected." (PMID 34217228, 2021). "In this regard, CTCs from the CSF of patients with LM from EGFR-mutated or ALK-rearranged NSCLC have a highly concordant molecular profile (89.5%) with a paired primary tumor." (PMID 34207653, 2021). "Taken together, it is plausible that the F129L‐activating mutation in MAP2K1 is an acquired mutation that leads to tumor resistance to ALK‐Is." (PMID 34058070, 2021). "These alterations can cause constitutive expression and activation of the ALK protein, leading to oncogenic phenotype and tumor pathogenesis." (PMID 34834454, 2021). "In another study, ALK mutations were outlined in circulating tumor cells from ALK-rearranged NSCLC patients who had progressive disease upon crizotinib or lorlatinib." (PMID 33572278, 2021). "In our study, the prevalence of EGFR mutation in tumor cells was 45.55%, ALK rearrangement 8.11%, ROS-1 rearrangement 2.56%, which was similar to the results of other studies 23-25." (PMID 33859531, 2021). "The prevalence of EGFR mutation in tumor cell was 45.55%, ALK rearrangement 8.11%, ROS-1 rearrangement 2.56%, PD-L1 expression positive 59.01%." (PMID 33859531, 2021). "Only 10% of tumor cells featuring mesenchymal properties harbored the ALK L1196M mutation, which means that 90% of these mesenchymal-type tumor cells had developed crizotinib resistance, while no ALK mutation was present." (PMID 33572278, 2021). "Overall, 54% of ceritinib-resistant tumor specimens harbored ALK resistance mutations, and 17% contained more than two different ALK resistance mutations, with G1202R (21%) and F1174C/L (16.7%) being the most common ones." (PMID 33572278, 2021). "For the ALK mutation-positive group, the radiomic score consisted of the tumor number (coef: 3.05), and an intensity feature exacted from edema area (coef: −1.76)." (PMID 33747933, 2021). "No patients in the enrolled cohort had a known BRAF or EGFR mutation or an ALK rearrangement in their primary tumor." (PMID 34642329, 2021). "MYCN and ALK gains of 3.7 and 2.9, respectively, were detected in a patient with 4 and 3 copies, respectively, as found in matched diagnostic tumor DNA by SNP array analysis." (PMID 34282791, 2021). "Conversely, the ALK L1196M mutation was hardly present in tumor cells that featured a predominantly mesenchymal pattern." (PMID 33572278, 2021). "The authors found that the association has a synergistic activity and leads to enhanced tumor regression and event-free survival in mouse models with ALK mutations, compared with the drugs used alone." (PMID 34885651, 2021).
tumor (continued). "Further, in those double mutated tumors, combination treatment with the ALK inhibitor Crizotinib and Torin-2 reduced tumor growth and partly initiated tumor regression." (PMID 33390782, 2021). "To understand the relative importance of ALK in the development of NB we compared the frequency of ALK mutations in NB with the frequencies of ALK mutations in other tumor types." (PMID 34103089, 2021). "The information derived from these ctDNA assays revealed the complex mutational kinetics of ALK+ tumors across therapy lines, as well as the increasing genomic instability of the tumor after sequential TKI treatments." (PMID 34876698, 2021). "The tumor microenvironment (TME) in ALK-rearranged caners includes interaction of tumor-associated macrophages (TAMs), CD4+ T cells, CD8+ T cells, regulatory T cells (FOXP3+) and mast cells." (PMID 33806977, 2021). "The authors of this study found tumor lesions with a mesenchymal phenotype and ALK resistance mutations to co-exist in one and the same tumor lesion." (PMID 33572278, 2021). "Tirosine kinase inhibitor crizotinib has shown promising results especially in tumours harbouring ALK mutation." (PMID 34801049, 2021). "One previous study also found that high tumor expression of YAP in NSCLC patients with the ALK fusion mutation was correlated with a poor response to ALK inhibitors." (PMID 32466572, 2020). "Recent studies have found that driver mutations (including EGFR and ALK mutations) are highly inconsistent among MPLCs, emphasizing the need to separately analyse gene mutation status in multifocal tumours." (PMID 32690092, 2020). "We used the one‐way ANOVA analysis, correlation analysis, and multiple logistic regression analysis to evaluate the relationship between the level of serum tumor markers and ALK mutations." (PMID 31489711, 2020). "The presence of other molecular abnormalities, such as EGFR, KRAS, BRAF or HER2 mutations and ALK rearrangements, has also been identified in some of these tumours." (PMID 31598903, 2020). "This is an ALK Q1275R alteration in which the tumor displayed increased variant allele frequency from time of diagnosis to time of relapse." (PMID 33384420, 2020). "We then used correlation analysis and multivariate logistic regression analysis to further evaluate the relationship between serum tumor markers and ALK mutations." (PMID 31489711, 2020). "Molecular analysis revealed that the tumor harbored ALK rearrangement and BRAF mutations simultaneously." (PMID 32991441, 2020). "ALK for tumor tissue was confirmed by ALK protein staining (ALK CDx assay) using the Ventana ALK (C5F3) companion diagnostic test (Roche Diagnostics, Indianapolis, IN, USA)." (PMID 32549278, 2020). "Studies have shown that although the positive rate of PD‐L1 in tumor specimens with EGFR/ALK mutations is high, the ratio of high levels of CD8+TILs is very low, which limits the antitumor effect of anti‐PD‐1/PD‐L1 monoclonal antibody." (PMID 32875727, 2020). "Most of the baseline clinical characteristics including age, sex, ECOG PS, histology, EGFR and ALK mutation status, PD‐L1 tumor proportion score, CRT protocol and timing of durvalumab initiation were similar between the high and low NLR groups." (PMID 32281272, 2020). "In this latter case, we stratified patients who presented EGFR mutation or MET, ROS1 or ALK translocation, herein defined as mutated (Mut+), and compared them to the levels of tumor-associated caspase-4." (PMID 33187551, 2020). "At the molecular level, ALK-positive NSCLC is of the lowest tumor mutational burden, which possibly accounts for the high initial response to TKIs." (PMID 32872120, 2020). "Tumor NGS can help monitor tumor dynamics and detect acquired ALK resistance mutations in crizotinib-resistant patients." (PMID 32010431, 2020).
tumor (continued). "An AGK‐BRAF fusion was newly identified in tumor from a donor with a known echinoderm microtubule‐associated protein‐like 4 to anaplastic lymphoma kinase (EML4‐ALK) fusion and history of anaplastic lymphoma kinase (ALK) inhibitor therapy." (PMID 31747139, 2020). "This study of 105 NBs shows that ALK mutations can be observed in tumours of various clinical stages and of various genomic profiles." (PMID 30778092, 2019). "CTC characterization analysis demonstrated that CTCs captured by NanoVelcro well reflect the ALK mutation status in tumor tissue, the ratio of ALK-rearrangement in CTCs positively correlated to that in tumor tissue." (PMID 30658713, 2019). "Among these spurious candidates were predicted pathogenic mutations in known oncogenic and tumor-suppressor genes, such as ALK and NF2, potentially confounding patient diagnosis." (PMID 30902988, 2019). "The better therapeutic efficacy of ceritinib relative to crizotinib can be partly associated with a broader coverage of ceritinib treatment for multiple tumor clones, particularly for those with crizotinib‐resistant ALK mutations." (PMID 31613427, 2019). "Their observations illustrate the role of activated ALK kinase in both tumor predisposition and normal development of the nervous system, and shed light on the pleiotropic role of ALK in humans." (PMID 30813562, 2019). "Traditionally, the ALK mutation can only be tested in the tumor biopsy, which is very difficult to obtain under certain circumstance." (PMID 30658713, 2019). "Our analysis of the relapsed tumor tissue sample revealed an ALK F1174L mutation and together with an ALK amplification." (PMID 31747416, 2019). "Treatment of ALK− ALCL tumor bearing mice carrying JAK1 and STAT3 mutations with ruxolitinib, a JAK1/JAK2 inhibitor, led to inhibition of tumor formation, which demonstrates the therapeutic potential of targeting the JAK1/STAT3 pathway." (PMID 31684088, 2019). "In this study, ALK-rearrangement CTC was consistently detected in all patients harboring this mutation confirmed by the tumor specimen." (PMID 30658713, 2019). "ALK activating mutations were reported in a subset of aggressive neuroblastomas, a pediatric tumor arising from precursor cells of the sympathetic nervous system." (PMID 31052302, 2019). "In recent studies of NSCLC, liquid biopsy was shown to detect driver gene mutations, such as EGFR and anaplastic lymphoma kinase (ALK) mutation, and tumor mutational burden." (PMID 31652678, 2019). "ALK mutations with a variant allele frequency less than 20% were detected in six tumours while ten other cases showed ALK mutations with higher variant allele frequency (between 20–60%)." (PMID 30778092, 2019). "EMT and ALK mutations were recently found to co-exist and separately contribute to resistance in the same crizotinib-resistant tumor lesions." (PMID 31653970, 2019). "ALK mutations in NB are found in equal frequencies across all tumour risk groups but appear to be associated with MNA, likely representing a cooperative effect between these oncogenes." (PMID 31088252, 2019). "Nevertheless, treatment options with TKIs and ALK inhibitors are limited to a minority of patients, harboring targetable EGFR or ALK mutations in their tumor cells, and rates of acquired therapy resistance remain very high in clinical settings." (PMID 30859681, 2019). "Because the patient had never smoked, we searched for driver mutations and found that the tumor harbored ALK rearrangement." (PMID 29744229, 2018). "In one small study, some patients who relapsed on ceritinib were found to have acquired new tumor mutations in the ALK kinase domain, either at position G1202 or at position F1174." (PMID 30453899, 2018).
tumor (continued). "Like TRK kinases, ALK gene rearrangements and dysregulated signaling are associated with a growing number of neoplasms." (PMID 29617282, 2018). "A previous study showed that ALK E1210K conferred resistance to crizotinib in vitro, and our whole exome sequencing analysis revealed that the ALK E1210K mutation occurred in the crizotinib-resistant xenograft tumor, crizotinib-6." (PMID 29764505, 2018). "ALK signaling pathway is often retained when the ALK fusion gene has a second mutation or increased copy number in the kinase domain and plays a role in tumor survival and drug resistance." (PMID 29455664, 2018). "In the ALK mutated cell lines the combination was synergistic, whereas in xenografts, the combination resulted in complete and sustained tumor regression and prolonged EFS compared to either single agent alone." (PMID 30326621, 2018). "Response here is significantly longer than that observed in ALK positive tumours, partly due to the natural history of ROS-1 mutated tumours, which tend to run a more indolent course." (PMID 30021993, 2018). "ALK is the most common somatically mutated gene in NB, with mutations present in around 9% of primary NB tumours and approximately 14% in the high-risk setting." (PMID 29642598, 2018). "This is consistent with the differential sensitivity of ALK mutants to crizotinib, since 3/7 tumours from patients with progressive disease harboured the resistance-conferring ALK F1174L mutation." (PMID 29642598, 2018). "The ALK resistance mutation L1198F induced by lorlatinib, however resensitize tumor cells to crizotinib." (PMID 30326973, 2018). "Upon relapse on lorlatinib, a biopsy revealed that the tumor had an ALK L1198F mutation, in addition to C1166Y." (PMID 29455675, 2018). "ALK mutations, e.g., germline ALK R1275Q, enable the constitutive activation of the kinase domain, which drives tumor cell malignancy and in vivo tumorigenicity." (PMID 29515255, 2018). "With regard to ALK-dependent mechanisms, we observed an ALK G1269A mutation in the resistant tumor of patient ALK4." (PMID 29300322, 2018). "Another group has recently shown that a combination of ceritinib, an ALK inhibitor, and CGM097, a MDM2 inhibitor, showed increased anti-tumour activity, and attenuated resistance to the ALK inhibitor in ALK-mutated NB cells." (PMID 29760954, 2018). "ALK is negatively associated with NB prognosis, with hyperactivating mutations of this kinase found in some of these aggressive tumours." (PMID 29555900, 2018). "The development of the technology to detect circulating tumor DNA offers the unique opportunity to detect longitudinally during patients’ treatment the mutational evolution of ALK and to serve as a guide for definition of optimal ALK inhibitor therapy." (PMID 30060526, 2018). "The other tumor models have a higher average mutation burden of 3.89 (Th-MYCN), 5.5 (Dbh-MYCN) and 4.75 (ALK) mutations per exome and exhibit a longer average time to tumor formation." (PMID 29492199, 2018). "In our study, we have explored ALK-independent mechanisms of crizotinib resistance in advanced NSCLC patients by comparing variants observed in the crizotinib-resistant tumor to the variants present in the tumor before crizotinib treatment." (PMID 29300322, 2018). "Second generation ALK inhibitors, such as ceritinib, alectinib and brigatinib were developed mainly due to ALK+ tumor resistance, arising from ALK mutations C1156Y, L1196M, G1269A, F1174L, 1151Tins, L1152R, S1206Y, I1171T, G1202, D1203N and V1180L." (PMID 29455659, 2018). "To focus on ALK-independent resistance mechanisms, we excluded genes that were mutated in ALK4 because the resistant tumor carried a known ALK-resistance-associated mutation (ALK G1269A) that explained the crizotinib resistance." (PMID 29300322, 2018). "Recent genome sequencing analyses of matched primary and relapsed NB tumours have shown an increased frequency of ALK mutations at relapse." (PMID 29642598, 2018).